STAT3 (signal transducer and activator of transcription 3)
Diseases named in the same sentence as STAT3 in open-access papers (continued):
Sharing a sentence is not in itself a finding about the gene and the disease.
pancreatic cancer (continued). "CAFs co-cultured with organoids derived from pancreatic cancer patients secrete IL-6, IL-11, and leukemia inhibitory factor (LIF), and these ligands activate a signal transducer and activator of transcription 3 (STAT3) in organoids." (PMID 33333727, 2020). "In a pancreatic cancer mouse model, activation of JAK2/STAT3 signaling promotes stromal formation in tumors and can lead to gemcitabine resistance." (PMID 33029256, 2020). "The functionality of these receptors was demonstrated in pancreatic tumor cell lines, which showed phosphorylation of ERK1/2 and STAT3 pathways in response to the respective recombinant interleukins." (PMID 31948053, 2020). "NE has also been shown to accelerate pancreatic cancer PNI and progression through the β-AR/PKA/STAT3 signaling pathway in vivo, where the activation of STAT3 upregulates the downstream expression levels of NGF and MMPs." (PMID 33392191, 2020). "IL-22 has been shown to increase the tumorigenicity and stemness of pancreatic cancer cells, through JAK/STAT3 signaling." (PMID 33042126, 2020). "Multiple studies using mouse models of pancreatic cancer demonstrate a strong relationship between Kras, NFKB, STAT3 and cytokine signalling which drives lesion formation and the development of PDAC51–57." (PMID 32541781, 2020). "Additionally, macrophages were shown to regulate skeletal muscle signal transducer and activator of transcription 3 (STAT3) – downstream target of IL-6 and key regulator of skeletal muscle mitochondrial homeostasis and proteostasis – during pancreatic cancer cachexia." (PMID 33364975, 2020). "In pancreatic cancer, HSP90 promoted VEGF-mediated angiogenesis via activating IL-6/HIF-1α/STAT3 autocrine loop." (PMID 32587480, 2020). "For example, IL-32α can inhibit JAK2 / STAT3 signaling pathway to inhibit IL-6-induced EMT and tumor cell invasion and metastasis in pancreatic cancer cells." (PMID 33097029, 2020). "Other researchers have reported that IL-32α can inhibit the JAK2/STAT3 signaling pathway and reverse the IL-6-induced EMT process in pancreatic cancer cells." (PMID 33097029, 2020). "Therefore, we could further scrutinize how nano-curcumin acts against PDAC and found that it raises ROS level inside pancreatic cancer cells to activate ER stress signaling and finally inhibit the phosphorylation of downstream effector STAT3, leading to cell apoptosis in the end." (PMID 32891174, 2020). "Two pancreatic cancer cell lines were treated with different concentrations of VPA with or without gemcitabine for the indicated time, and the expression of STAT3 was observed." (PMID 31244991, 2019). "A report about the regulation of SOCS3 in pancreatic cancer cells found out that, the restoration of miRNA let-7 promoted the expression of SOCS3 and then impeded the activation of STAT3." (PMID 31222560, 2019). "Very recently, alantolactone, a natural sesquiterpene lactone, was shown to down-regulate phospho-STAT3 and enhance EGFR inhibition by erlotinib or afatinib in pancreatic cancer." (PMID 31422383, 2019). "Our results suggest that STAT3/Bmi1 signaling cascade, which is regulated by ROS-dependent, AKT- or p38-modulated pathways, primarily mediated the sensitivity and motility of pancreatic cancer cells towards combined gemcitabine and VPA regimen." (PMID 31244991, 2019). "A recent study indicated that BRM promotes pancreatic cancer growth and chemoresistance via activation JAK2/STAT3 pathway." (PMID 31722744, 2019). "In pancreatic cancer cells, BITC induced apoptosis by inducing reactive oxygen species (ROS)-dependent STAT3 signals." (PMID 30970087, 2019).
pancreatic cancer (continued). "The circular RNA (circRNA) 100782 is upregulated in pancreatic cancer and its knockdown downregulates all miR-124 targets including IL6R and STAT3." (PMID 31557897, 2019). "In vitro data using pancreatic tumor cells lines provided a possible explanation: IL-21 activated ERK and STAT3 pathways and upregulated Blimp-1." (PMID 31540511, 2019). "In pancreatic cancer, NDRG1 acts as an anti-tumor factor by repressing proliferation and impeding invasion and migration of the proteins p-STAT3, PI3K, p-AKT, MMP2, MMP9." (PMID 31205821, 2019). "Most recently, MEL enhanced the efficacy of sorafenib against pancreatic cancer by downregulation of PDGFR-β/STAT3 cell signaling and MEL receptor (MT)-mediated STAT3 in PDAC cells." (PMID 30563247, 2018). "In addition, in pancreatic tumors with mutant SMAD4, matrix stiffening was associated with elevated ROCK activity that in turn stimulated increased production of ECM, assembly of focal adhesions and signal transducer, and activator of transcription-3 (STAT-3) signaling driving tumor progression." (PMID 29780748, 2018). "It has been reported that Stat3 was a critical factor to facilitate precursor formation and enforced MMP7 expression in pancreatic cancer cells, while MMP7 level was correlated with metastasis and survival in pancreatic cancer patients." (PMID 30428899, 2018). "Xn treatment was found to arrest cell cycle and induce apoptosis in pancreatic cancer cells (PANC-1, BxPC-3) via decreasing STAT3 phosphorylation and its downstream targeted genes expression, such as cyclin D1, survivin, and Bcl-xL." (PMID 29872398, 2018). "In conclusion, CuB treatment had a strong growth inhibitory effect in pancreatic cancer cells by decreasing EGFR levels and downstream signaling of PI3K/Akt/mTOR and STAT3." (PMID 29262554, 2017). "In this study, we demonstrate for the first time that CuB inhibits pancreatic cancer cell proliferation by interfering with EGFR levels and downstream signaling of PI3K/Akt/mTOR and STAT3." (PMID 29262554, 2017). "Pancreatic cancer sphere cultured from the CFPAC-1 cells showed elevated expression of PAUF and pluripotent stemness genes (Oct4, Nanog, Stat3, and Sox2), and the mRNA of PAUF were increased in CD44+CD24+ESA+ pancreatic CSCs." (PMID 29100320, 2017). "Similar results were observed for STAT3 phosphorylation on serine-727 and CCR1 mRNA expression in T24 bladder and Capan-1 pancreatic cancer cells expressing AKT1 shRNA." (PMID 29212252, 2017). "According to our previous study, EGFR, functioning as a REG3A receptor, mediated the REG3A signal-promoting human pancreatic cancer cell growth and JAK2/STAT3 activation." (PMID 28880262, 2017). "Alpha-mangostin has been known to possess the antioxidant and antitumor property, probably via reduction of NF-κB, Stat3, and MMP9 expression and inhibits pancreatic tumor growth in vivo." (PMID 28537893, 2017). "By targeting STAT3, Lip-FLLL32 inhibits both proliferating pancreatic cancer cells and pancreatic cancer stem cells, resulting in reversal of radioresistance induced by CSCs." (PMID 26887043, 2016). "In conclusion, we describe the delivery of a STAT3 inhibitor, FLLL32, by liposomes, which improves not only the bioavailability of FLLL32 but also the selective distribution of FLLL32 to pancreatic tumors." (PMID 26887043, 2016). "The objective of this study was to determine the mechanism of action of a novel antimitotic and Stat3 inhibitor, LTP-1, on human pancreatic cancer in vitro and in vivo." (PMID 27278358, 2016). "Inflammation-induced activation of STAT3 and NFκB promotes the survival, proliferation and EMT of tumor cells, thus contributing to the development and progression of pancreatic cancer." (PMID 27413117, 2016). "As an effective inhibitor for Jak2/STAT3 pathway, AG490 reversed pancreatic cancer cell-induced inhibition of DC differentiation." (PMID 27556503, 2016).
pancreatic cancer (continued). "Recent studies demonstrate that signal transducer and activator of transcription 3 (STAT3) plays critical roles in initiation and progression of pancreatic cancer, especially in mutant KRAS-mediated pancreatic ductal adenocarcinomas (PDAC)." (PMID 26887043, 2016). "It induces metabolic reprogramming in pancreatic cancer cells by reducing expression of a key metabolic regulator, c-MYC, through reduced activation of STAT3." (PMID 26510913, 2015). "Recently, STAT3 has been reported to suppress LC3 expression, thereby inhibiting autophagy and growth of pancreatic cancer cells." (PMID 26458814, 2015). "Recently, we demonstrated that protein kinase C iota (PKCι) and zeta (PKCζ) promote pancreatic cancer transformed growth and invasion, by activating Rac1→ERK and STAT3 signaling pathways, respectively." (PMID 25915428, 2015). "In ERBB2-STAT, these genes are involved in pancreatic cancer and signal transduction pathways; the correlation between the activation of ERBB2 and STAT3 has been observed in many human tumors." (PMID 23940583, 2013). "Since STAT3 is constitutively active in pancreatic cancer cells, we next examined the effects EGCG on STAT3 expression by immunofluorescence." (PMID 22348037, 2012). "In conclusion, our findings provide unprecedented insights into the STAT3 signaling pathway by which EGCG inhibits viability, invasion and migration, and induces apoptosis in pancreatic cancer cells." (PMID 22348037, 2012). "As next steps, we will evaluate STAT3 and APE1 as molecular targets in xenograft models of human pancreatic cancer." (PMID 23094050, 2012). "Since APE1/Ref-1 also exerts redox control on other cancer-associated transcription factors, we assessed the impact of dual-targeting of STAT3 signaling and APE1/Ref-1 redox on pancreatic cancer cell functions." (PMID 23094050, 2012). "We provide evidence that BITC dose-dependently inhibits the migration, invasion, and neovascularization of human pancreatic cancer and endothelial cells by targeting HIF1α, VEGF, MMP-2, and Rho-GTPases through the STAT-3 dependent pathway." (PMID 22016776, 2011). "Activation and blocking of the Stat3 signaling pathway can affect invasion ability and expression of the VEGF and MMP-2 genes in pancreatic cancer cells." (PMID 20482858, 2010). "Studies demonstrate that radiation enhances glycolysis in pancreatic cancer cells, raising lactate levels and promoting MDSC activity via the GPR81/mTOR/HIF-1A/STAT3 pathways, thus contributing to an immunosuppressive microenvironment and tumor progression, recurrence, and radioresistance." (PMID 41424847, 2026). "In some pancreatic cancer models, STAT3-driven survival is found even when PI3K/AKT is not chronically activated." (PMID 41596231, 2026). "To investigate whether cytokines and cellular stress stimulate ITGB3 expression in a STAT3-dependent manner, we developed STAT3 CRISPR knockout (KO) clones in FG pancreatic cancer cells." (PMID 40701148, 2025). "ADAM8 regulates intracellular STAT3 levels via miR-181a-5p and NEAT1 in pancreatic cancer." (PMID 39412616, 2025). "In pancreatic cancer patients, an intake of 8 g/day of curcumin for two months resulted in a significant downregulation of pro-inflammatory and pro-survival signals, including NF-κB, COX-2, and STAT3, in peripheral blood mononuclear cells (PBMCs)." (PMID 41515171, 2025). "The circular RNA circPTPN22 enhances STAT3 acetylation by inhibiting its interaction with the deacetylase SIRT1, which promotes cancer progression and suppresses antitumour immunity within the pancreatic cancer microenvironment." (PMID 41463025, 2025).
pancreatic cancer (continued). "Besides, MARCH8 facilitated the proliferation and metastasis of pancreatic cancer by inducing the degradation of PTPN4 protein and thereby activating the STAT3 phosphorylation." (PMID 40145330, 2025). "Notably, HPSC‐CM exhibited significantly weaker activation of the STAT3 signaling pathway compared to CAFs‐CM, indicating that CTHRC1 in CAFs plays a critical role in activating this pathway in pancreatic cancer cells." (PMID 40751418, 2025). "Inhibiting STAT3 can reduce noradrenaline-induced expression of NGF, matrix metallopeptidase (MMP) 2, and MMP 9, as well as diminish the migratory and invasive capabilities of pancreatic cancer cells." (PMID 40940782, 2025). "To further explore the detailed molecular mechanism and signaling pathway by which CTHRC1 in CAFs regulates the progression of pancreatic cancer, we reviewed the literature and found that existing studies have confirmed that LIF mainly acts by activating the STAT3 signaling pathway." (PMID 40751418, 2025). "Our present study revealed that the STAT3 signaling pathway is partially regulated by ADAM8 in pancreatic cancer, but only the STAT3 protein, not its mRNA, is dependent on ADAM8 expression." (PMID 39412616, 2025). "YY002 is another small-molecule therapeutic for pancreatic cancer that targets the STAT3 SH2 domain but, unlike N4, it blocks both pY705 and pS727." (PMID 40075607, 2025). "However, thiostepton can inhibit STAT3 and GPX4 signaling to induce ferroptosis in pancreatic cancer cells, which is inconsistent with our findings." (PMID 38444939, 2024). "The most promising lead, YY002, a highly potent and selectiveSTAT3 inhibitor, inhibited STAT3 Tyr705 and Ser727 phosphorylation,thereby abrogating the STAT3 nuclear and mitochondrial functions.YY002 potently inhibited pancreatic cancer growth and metastasis in vitro and in vivo." (PMID 38559310, 2024). "In summary, we present a novel small-moleculeSTAT3 inhibitor YY002,which simultaneously inhibited STAT3 Tyr705 and Ser727 phosphorylation.YY002 potently inhibited pancreatic tumor growth and metastasis, andalso exhibited favorable pharmacokinetics and an acceptable safetyprofile." (PMID 38559310, 2024). "To detect signaling pathways that may be involved in pancreatic cancer cell death through TLR2 and TLR9 intrabody-mediated intracellular inhibition, we performed a Western blot analysis of STAT3 phosphorylation changes in the treated cells." (PMID 38390872, 2024). "Subsequently, exosomal miR‐199a‐3p secreted from CAAs and taken up by surrounding pancreatic cancer cells suppressed SOCS7 expression, leading to STAT3 activation and increased SAA1 expression, ultimately resulting in a more aggressive phenotype in pancreatic cancer cells." (PMID 39431622, 2024). "Mechanistically, STAT3 binds to GPX4 and regulates its expression in pancreatic cancer cells." (PMID 38575966, 2024). "Furthermore, numerous studies have demonstrated the unusually high activation of the IL-6/JAK2/STAT3 signaling pathway in a range of malignancies, including gastric, breast, liver, colorectal (CRC), colon, ovarian (OC), lung, and pancreatic cancers." (PMID 38666938, 2024). "To further analyze whether STAT3 can be activated by IL15RA, we used small interfering RNA to silenceIL15RA in pancreatic cancer cells." (PMID 39396119, 2024). "In addition, the IL-6/STAT3 signaling pathway can methylate the SOCS3 via DNMT1, leading to pancreatic cancer progression and metastasis." (PMID 39195299, 2024). "Additionally, in pancreatic cancer cells, quercetin prevented EMT by obstructing the signal transducer and activator of transcription 3 (STAT3) signaling pathway, reversed interleukin-6 (IL-6)-induced EMT, and consequently decreased cancer cell invasion." (PMID 37446730, 2023).
pancreatic cancer (continued). "Ferroptotic pancreatic cancer cells releasing KRASG12D can be taken up by macrophages through an autophagy-dependent mechanism, which polarizes macrophage to an M2-like phenotype through STAT3-dependent fatty acid oxidation." (PMID 37152291, 2023). "We found that BA could reduce the expression of IL-6 and the ratio of p-STAT3/STAT3 and p-AKT/AKT by mediating miR-365/BTG2, which may be one of the mechanisms of BA in anti-pancreatic cancer." (PMID 37415745, 2023). "When pancreatic cancer cells were treated with the MS extract, the expression of MMP9, β-catenin, and vimentin decreased in a concentration-dependent manner, and the phosphorylation of STAT3 also decreased." (PMID 37550432, 2023). "Overexpression of circFARP1 in CAFs confers GEM resistance in pancreatic cancer cells by enhancing the expression and secretion of LIF in CAFs, thereafter activating the STAT3 signaling pathway and increasing the expression of several GEM resistance-associated factors, including ABCC2, CDA and SOX2." (PMID 35045883, 2022). "Co-targeting STAT3 and EGFR or STAT3 and SRC suppressed cell growth in pancreatic cancer." (PMID 35600368, 2022). "Other studies have also confirmed that STAT3 regulates ferroptosis in various forms, but its role in pancreatic cancer has not been reported." (PMID 35859150, 2022). "STAT3 inhibition (STAT3i) resulting in ERK activation may be involved in other mechanisms in ESCC and has been studied in pancreatic cancer." (PMID 35614034, 2022). "In line with our findings, CPT has been shown to inhibit the phosphorylation of STAT3 at Tyr705 in a dose-dependent manner, without noticeable effects on the total level of STAT3 in pancreatic cancer cells." (PMID 35606804, 2022). "Similarly, STAT3 signaling pathway activation induced by S100A16 also promoted the migration and EMT of pancreatic cancer cells." (PMID 36291659, 2022). "LncRNA H19 is significantly upregulated in pancreatic cancer cell lines and facilitates pancreatic cancer metastasis and EMT by directly targeting miR-675-3p, which binds to SOCS5, a member of the SOCS protein family that negatively regulates JAK2/STAT3 signaling." (PMID 35819532, 2022). "Thus, BITC is a strong anti-cancer agent effective against pancreatic cancer acting via inhibition of PI3K/AKT/FOXO-, STAT-3-, and STAT-3-mediated HIF-1α/VEGF/Rho-GTPases signaling axes." (PMID 36428575, 2022). "Although our previous studies showed that overexpressed ITGA2 can upregulate PD-L1 to activate the STAT3 signaling pathway and thereby promote tumor cell progression, the carcinogenic mechanism of ITGA2 in pancreatic cancer still needs elucidation in further research." (PMID 35193647, 2022). "Moreover, treatment by targeting both EGFR and STAT3 was demonstrated to play an important role in EGFR–STAT3 feedback loop blockade and restriction of pancreatic cancer volume." (PMID 35356799, 2022). "In pancreatic cancer, solute carrier family 39 member 4 (ZIP4) induces ZEB1 expression via STAT3 signaling and subsequently activate integrin α3β1 to regulate the JNK signaling pathway, leading to inhibit chemosensitivity by decrease gemcitabine transporter ENT1." (PMID 33406733, 2021). "Thus, if KRAS is mutated in pancreatic cancer cells, inflammatory signals cause further secretion of cytokines and also lead to dysregulated activation of STAT3 as positive feedback, fueling KRAS-driven pancreatic cancer." (PMID 33801246, 2021). "Pancreatic cancer promotes the formation of a pro-metastatic niche in the liver by secreting IL6 produced by non-cancer cells within pancreatic tumors, which activate proinflammatory STAT3 signaling in hepatocytes." (PMID 35154607, 2021). "So far there is nearly no anti-tumor drug directly acting on the STAT3 on the market except napabucasin, which was recently approved for pancreatic cancer and esophageal tumor treatment." (PMID 34922636, 2021).